KRT18 (keratin 18)
Diseases named in the same sentence as KRT18 in open-access papers (continued):
Sharing a sentence is not in itself a finding about the gene and the disease.
tumor (continued). "Immunocytochemical analysis showed that tumor liver MSCs and non-tumor liver MSCs are also positive for vimentin, α-SMA, and N-cadherin, and negative for epithelial markers cytokeratin 18 and E-cadherin." (PMID 31546729, 2019). "Notably, canonical breast cell differentiation genes and molecular markers (KRT8, KRT18, KRT14, TP63, ERBB2, ESR1, PGR) were not differentially expressed, suggesting the cells maintain their differentiation state and tumor subtype." (PMID 34741115, 2021). "In parallel, although CYH33 did not downregulate the percentage of Krt18+ cells, the proportion of Mki67+ cluster in Krt18+ cells decreased in Balb/c mice but not in nude mice on CYH33 treatment, indicating that tumor cells are less proliferative in immune-competent mice." (PMID 34373258, 2021). "A significant reduction in Krt18 expression was observed in +E2 versus −E2 D2.0R-inoculated mice suggesting that, in contrast to the MCF7 model, E2 may not promote tumor growth in the D2.0R model." (PMID 30250146, 2018).
infection (275 papers, 2008 to 2026). The state of being infected such as from the introduction of a foreign agent such as serum, vaccine, antigenic substance or organism. "The first model employs K18-hACE2 mice that are highly susceptible to lethal infection due to their expression of a transgene for the human ACE2 receptor under control of the keratin-18 promoter." (PMID 34889942, 2022). "At 72 h post-infection, actin forms a punctate-like pattern around the bacterial compartment, whereas tubulin and cytokeratin 18 associate around the bacterial compartment in a filamentous pattern." (PMID 33282747, 2020). "We next evaluated the K18-hACE2–transgenic (K18-hACE2–Tg) model (in which the human ACE2 gene is under the control of the human keratin 18 promoter) in the IFNAR-knockout (IFNAR-KO) B6 background for susceptibility to infection." (PMID 35834347, 2022). "Here, we show that transgenic mice expressing the human SARS-CoV-2 receptor (angiotensin-converting enzyme 2 [hACE2]) under a cytokeratin 18 promoter (K18) are susceptible to SARS-CoV-2 and that infection resulted in a dose-dependent lethal disease course." (PMID 32803199, 2020). "At 18 and 24 h post infection (p.i.), both cultures showed similar percentages of cells with apoptosis-specific cytokeratin 18 cleavage (M30-positive cells) in comparison to uninfected control cultures." (PMID 23922974, 2013). "Within the BM, Krt18 is almost exclusively expressed in HSCs and these mice do not have any immunological impairment that would change the severity of our infection model." (PMID 35166205, 2022). "As expected, KRT18-hACE2 mice were most sensitive to infection and succumbed to BavPat1 infections." (PMID 35023830, 2022). "K18‐hACE2 transgenic mice, in which hACE2 expression is driven by the human epithelial cell cytokeratin‐18 (K18) promoter, has been used for studying the pathogenesis of SARS‐CoV28 and SARS‐CoV‐229 and can cause lethal infection." (PMID 34909757, 2021). "Transgenic mice (K18-hACE2) expressing the human SARS-CoV-2 receptor human angiotensin-converting enzyme (hACE2) under a cytokeratin 18 (K-18) promoter are susceptible to SARS-CoV-2, and infection resulted in a lethal disease course." (PMID 34835197, 2021). "However, transgenic mice expressing hACE2 driven by a cytokeratin 18 promoter (K18) are highly susceptible to SARS-CoV-2, and infection results in a dose-dependent fatal disease course with the specific characteristics of a higher viral titer in the lungs and neuroinvasion." (PMID 36748729, 2023). "However, KRT18-hACE2 mice are overly susceptible as they develop deadly SARS-CoV-2 encephalitis (in addition to pneumonia) in response to low infection doses due to nonphysiological and broad (over)expression of hACE2." (PMID 35023830, 2022). "K18-hACE2-transgenic mice, in which hACE2 expression is powered by the epithelial cell cytokeratin-18 (K18) promoter, were originally designed for the study of SARS-CoV pathogenesis and lead to a lethal infection model." (PMID 34349145, 2021). "Genes for epithelial cell markers such as cytokeratins 14, 18 and 19 (KRT14, KRT18, KRT19), E-cadherin (CDH1) and epithelial cell adhesion molecule (EPCAM) showed the highest expression at 0 hpi and decreased post-infection." (PMID 34740333, 2021). "For example, the expression levels of some DEGs enriched in “negative regulation of apoptosis” functional pathway were up-regulated after infection, but other DEGs’ expression levels were down-regulated (including FAIM, CAT and KRT18)." (PMID 29073164, 2017). "Immunofluorescence analysis of fixed PMECs infected with recombinant E. coli O111:K58 showed positive staining for cytokeratin-18, a specific marker of the epithelial cell lineage, and adherent RFP-enriched E. coli was detected on the surface of PMECs at 6 h after infection." (PMID 32823867, 2020).
infection (continued). "The expression of hACE2 via the keratin 18 promoter in the K18-hACE2 mice did not lead to overtly aberrant cell tropism in the lungs, with infection of bronchial and alveolar epithelia cells by omicron variants also described in settings where hACE2 is not expressed as a transgene." (PMID 39531435, 2024).
cancer (215 papers, 1996 to 2026). A tumor composed of atypical neoplastic, often pleomorphic cells that invade other tissues. "Ablation of serine 52 phosphorylation on keratin 18 by mutation to an alanine residue leads to protein softening in cancer cells." (PMID 36587764, 2023). "This is consistent with previous observations that, both KRT8 and KRT18 are over-expressed/aberrantly expressed in certain human cancers and such expression is associated with cancer progression/poor-prognosis." (PMID 34490045, 2021). "A good example of this is Keratin 18, which is a component of cytokeratin 8/18 intermediate filaments and has long been used as a marker for apoptosis in cancers, but the loss of keratin 18 expression in cells is associated with EMT." (PMID 31080560, 2019). "Cytokeratin 18 (CK18), a type I cytokeratin of the intermediate filament family, has been associated with the prognosis of cancer patients for decades." (PMID 29437899, 2018). "Dysregulation of KRT18 is linked to the development and progression of a wide range of cancers." (PMID 38319721, 2024). "Keratin 18 represents a robust diagnostic and prognostic biomarker for human cancers." (PMID 36949761, 2023). "Subsequently, KRT18 was found to be abnormally expressed in various malignant tumours and was gradually regarded as a diagnostic and prognostic marker in cancers, including gastric cancer, non–small cell lung cancer, hepatocellular cancer, and colorectal cancer." (PMID 37620903, 2023). "KRT18, a cytoskeletal protein essential for cellular integrity, is suggested to be overexpressed in most cancer types, including liver, colon, and NSCLC, and is associated with their advanced clinical stage, metastasis, malignant status, and poor prognosis and survival in patients." (PMID 35745691, 2022). "Literature data suggest that epithelial tumor cell aggressiveness is characterized by epithelial-mesenchymal transdifferentiation (EMT) with aggressive cancers characterized by loss of cell-cell adhesion, repression of E-cadherin and cytokeratin 18 (K18), and increased cell mobility." (PMID 24900952, 2014). "EpH4-Snail cells exhibited coexistence of the mesenchyme-specific intermediate filament Vimentin and the epithelium-specific Cytokeratin-18, which is a typical feature of a hybrid E/M state of cancer cells." (PMID 41521893, 2026). "The epithelial OC origin of the PDC2 and PDC3 samples was confirmed by the expression of OC-specific markers PAX8 and CD24, epithelial makers MKI67, EPCAM, KRT8 and KRT18 and cancer stem cell markers such as CD44 and ROR1." (PMID 39482470, 2025). "The non-immune cells included endothelial cells (PVALP and PECAM1), CAFs (COL1A1 and COL1A2), and cancer cells (KRT18 and VEGFA)." (PMID 38216635, 2024). "These included, but were not limited to: PECAM1 and CDH5 (EC markers), PDGFRA (fibroblast marker), PDGFRB (pericyte marker), and EPCAM and KRT18 (cancer cell markers)." (PMID 38183074, 2024). "Cytokeratin 18 is an intermediate filament expressed in epithelial carcinoma and is diminished in basal subtypes, contrary to vimentin, which is implicated in the migration mechanism." (PMID 39201674, 2024). "Among the upregulated genes we noticed markers those were associated with cancer genesis and development, including SOX4, SPINK1, CEACAM6, KRT8 and KRT18." (PMID 37957625, 2023).
cancer (continued). "Some markers CD14 (monocyte), CD3D (CD4+T cells), CD3E (CD8+T cells), CD68 (macrophage), CST3 (myeloid cells), GNLY (NK cells), KRT18 (epithelial cells), and NKG7 (NK cells) were positively associated with TMSB10 in all cancers." (PMID 37275863, 2023). "We also confirmed that NIS-GFP expressing cells were indeed human cancer cells through staining with anti-human cytokeratin-18 (CK-18)." (PMID 37359535, 2023). "We employed real-time quantitative reverse transcription polymerase chain reaction (qRT‒PCR) to assess the expression levels of three biomarkers, vimentin, KRT16, and KRT18, associated with metastasis and EMT in cancer cells following a 48-h hypoxia treatment." (PMID 37780810, 2023). "For example, CD3E and CD2 were highly expressed in T cells, CD79A was highly expressed in B cells and KRT18 was highly expressed in cancer cells." (PMID 36681772, 2023). "Our results confirmed that hypoxia treatment upregulated the expression of vimentin and KRT16 while downregulating the expression of KRT18 in both cancer cell types, indicating the upregulation of EMT and metastasis." (PMID 37780810, 2023). "The authors of the second study discovered that XH inhibited ESCC cell proliferation and induced apoptosis by targeting keratin-18 (KRT18), which plays a crucial role in maintaining of tissue integrity and is often over-expressed in different cancer types." (PMID 37373500, 2023). "While some cancer-associated genes were downregulated, such as potassium channel 6.1 (Kir6.1), the atypical cadherin, FAT2, and keratin 18 (Krt18)." (PMID 35572581, 2022). "LINC02470 and SMAD3 were more highly expressed in high-grade cancer cells with higher mesenchymal-like traits, such as higher N-cadherin and vimentin expression but lower E-cadherin and cytokeratin 18 expression." (PMID 35205713, 2022). "Cancer cells were characterized by strong expression of canonical mammary epithelial cell markers, Epcam and Cd24, and including luminal markers Krt8 and Krt18, consistent with the luminal progenitor nature of MMTV‐PyMT tumors." (PMID 35611998, 2022). "The results showed that KRT18 selectively affects genes enriched in DNA-dependent transcription and metabolic process pathways related to cancer development at transcriptional level." (PMID 34290732, 2021). "KRT18 is a cytokeratin in epithelial and endothelial cells reported to be aberrantly expressed and regarded as a biomarker and important regulator in many cancers, including GC." (PMID 34290732, 2021). "The expression pattern of the cancer-related DEGs showed a high consistency of the KRT18-affected transcription in three biological replicate datasets." (PMID 34290732, 2021). "Beyond this, KRT18 affects the alternative splicing of genes enriched in apoptosis, cell cycle, and other cancer-related pathways, which were then validated by reverse transcription–quantitative polymerase chain reaction approach." (PMID 34290732, 2021). "The epithelial markers Ep-CAM (CD326) or cytokeratin 18 (CK18) are suitable markers for the detection of carcinoma cells." (PMID 34910301, 2021). "A number of gene nodes linked to drug resistance in other cancer types (including CAT, TRIM59, ANXA2, ADM, AJUBA, HSPA1A/1B, LAMC2, TRIM14, KRT8, KRT18, KRT9, CLDN1, and SMARCA2) were also down-regulated in PARPis-sensitive AsPCs." (PMID 33213473, 2020). "Multiple studies have reported that KRT18 can be used both as a biomarker and regulator in many diseases, including cancers." (PMID 33330500, 2020).
cancer (continued). "We also detected enrichment for transcripts encoding fibroblast-specific protein 1 (FSP1/S100a4), keratins Krt7, Krt8, Krt14 and Krt18 and claudins Cldn3, Cldn4 and Cldn7 in this cluster which were also enriched in epithelial/cancer cells." (PMID 32455670, 2020). "In our research, KRT18 protein expression was markedly increased in CRC cancer tissues and cell lines compared with adjacent normal colorectal tissues and normal colonic epithelial cell line, respectively." (PMID 31345960, 2019). "On the other hand, serum level of cytokeratin 18 reflects the released CK18 by dying cancer cells, while the tissue expression level of CK18 usually reflects the differentiation status of the tissues." (PMID 29437899, 2018). "Both immunofluorescent (Fig 1CLeft) and immunohistochemical (Fig 1CRight) staining demonstrated that the cells from ascites fluid expressed keratin 18, which suggested they were exfoliated cancer cells, and many were also highly positive for L1-CAM/CE7." (PMID 26761817, 2016). "The biological and clinical significance of cytokeratin 18 (CK18) expression by numerous carcinomas has been reported." (PMID 26267323, 2015). "Other markers, EZR and KRT18 already exhibit characteristics of the aberrant expression observed in carcinoma within the adenomatous polyps." (PMID 25423035, 2014). "Cytokeratin 18 is expressed by most carcinomas, including those of breast, prostate, lung and colon." (PMID 22933944, 2011). "Noticeably, cytokeratin 18 mRNA was more abundant in androgen-independent cancer samples than BPH, in agreement with our previous observations in immunofluorescence." (PMID 19763272, 2009). "This is often accompanied by the aberrant expression of specific proteins that may be used as a cancer biomarker such as KRT18." (PMID 37439806, 2024). "Cytokeratin 18 exhibits overexpression in many types of cancer originating from epithelial organs." (PMID 37510802, 2023). "Malignant cells were identified using epithelial markers such as EPCAM and KRT18, and nonmalignant cells were annotated as myeloid immune cells, B cells, plasma cells, T cells and cancer-associated fibroblasts according to canonical markers." (PMID 36739462, 2023). "In addition, keratin 18 enhances the expression of cell adhesion molecules and reduces cancer aggressiveness in vivo." (PMID 37371778, 2023). "Cytokeratin 18 is an intermediate filament protein highly expressed in carcinoma cells." (PMID 38132110, 2023). "We then subset and clustered the epithelial lineage cells and identified the normal acinar (Amy1+ and Amy2a2+) and islet/ductal cells (Pyy+ and Sst+, Ins1+ and Ins2+) as well as a cancer cell cluster with normal epithelial lineage marker expression excluded (Sox9+ and Krt18+)." (PMID 35941362, 2022). "Therefore, it is unsurprising that both keratin 18 and keratin 8 are often upregulated in most human cancer types." (PMID 35406424, 2022). "Moreover, earlier studies also showed that an increase in the protein abundance of both keratin 18 and keratin 8 in cancer cells enhances the migratory and invasive capacities of cancer cells and alters their interactions with extracellular environments." (PMID 35406424, 2022). "Keratin 18 is one of cytoskeletal proteins and functions in various cancers." (PMID 36213576, 2022). "In addition to being a biomarker in cancers, increasing evidence has suggested that KRT18 is an important regulator in many diseases, including cancer." (PMID 34290732, 2021). "In addition to be a biomarker in cancers, increasing evidences have suggested that KRT18 is an important regulator in many diseases, including cancer." (PMID 34290732, 2021). "MF HSC/MPP showed a high expression of immune and inflammatory pathways (HLA genes, GBP4, and IFITM1), a matrix- and collagen-degrading enzyme (MMP2), and genes with oncogenic function (MYCN, KRT8, and KRT18) that have been correlated with cancer progression and poor survival." (PMID 34525349, 2021).